ENSG00000286116 (FAS antisense RNA 1)
Gene: Long non-coding RNA gene on chromosome 10 (88,990,045 to 88,994,249, reverse strand). Ensembl gene ENSG00000286116.
Gene Ontology:
Biological process: regulation of gene expression